APOL5 (apolipoprotein L5)
Description:
May affect the movement of lipids in the cytoplasm or allow the binding of lipids to organelles.
Synonyms: ApoL-V; APOLV
Tractability: Antibody: its Gene Ontology location is reachable by antibodies, with medium confidence.
Gene: Protein-coding gene on chromosome 22 (35,717,872 to 35,729,483, forward strand). Ensembl gene ENSG00000128313.
Subcellular location: Cytoplasm
Gene Ontology:
Molecular function: high-density lipoprotein particle binding; lipid binding
Biological process: lipid metabolic process; lipid transport; lipoprotein metabolic process
Cellular component: membrane; cytoplasm; extracellular region
Genetic constraint (gnomAD): Loss-of-function variants: 27 observed, 34.05 expected, observed/expected ratio (o/e) 0.79, 90% interval 0.58 to 1.09. The upper end of that interval is the gene's LOEUF score, 1.09, which puts it in group 4 of 6, group 1 being the genes least tolerant of losing a copy. Missense variants: 509 observed, 546.51 expected, observed/expected ratio (o/e) 0.93, 90% interval 0.87 to 1. Synonymous variants: 187 observed, 205.79 expected, observed/expected ratio (o/e) 0.91, 90% interval 0.81 to 1.03.
Homologues: Orthologues: chimpanzee APOL5 (96% identical), macaque APOL5 (79% identical), dog APOL5 (44% identical), zebrafish apol (16% identical), Caenorhabditis elegans F07F6.8 (8% identical), Caenorhabditis elegans F07F6.7 (7% identical). Paralogues in human: APOL6 (26% identical), APOL2 (22% identical), APOL3 (22% identical), APOL1 (21% identical), APOL4 (18% identical), APOLD1 (9% identical).
Diseases named in the same sentence as APOL5 in open-access papers:
APOL5 is named in the same sentence as 3 diseases in open-access papers, as found by Europe PMC text mining. Sharing a sentence is not in itself a finding about the gene and the disease. The quoted sentences say what the papers report.
schizophrenia (2 papers, 2021 to 2023). A major psychotic disorder characterized by abnormalities in the perception or expression of reality. "The function of APOL4 and APOL5 is unknown, apart from the lack of apoptotic activity for APOL4 and the genetic association of APOL4 with schizophrenia." (PMID 32530132, 2021).
neuroblastoma (1 paper, 2025). Neuroblastoma (NB) is the most common solid, extracranial childhood tumor. "Other notable genes include (i) NPBF3, part of the neuroblastoma breakpoint family; (ii) APOL5, from the apolipoprotein L gene family; (iii) CHIA, which plays a role in chitin degradation; and (iv) TTN, which encodes a prominent protein in striated muscle." (PMID 39774017, 2025).
APOL5 also shares sentences with these, for which no sentence is quoted: diabetes (1 paper).